TFPI2 (tissue factor pathway inhibitor 2)
Diseases named in the same sentence as TFPI2 in open-access papers (continued):
Sharing a sentence is not in itself a finding about the gene and the disease.
colorectal cancer (19 papers, 2013 to 2026). A primary or metastatic malignant neoplasm that affects the colon or rectum. "The goal of our study was to estimate the diagnostic value of TFPI2 hypermethylation in gastric cancer (GC) and colorectal cancer (CRC)." (PMID 29137404, 2017). "Analysis of the methylation status of the TFPI2 and NDRG4 genes in peripheral blood mononuclear cells has demonstrated high diagnostic potential, as both genes are hypermethylated in colorectal cancer." (PMID 40867261, 2025). "Lower TFPI2 levels in tumor cells correlate with poorer survival outcomes in breast, pancreatic, and colorectal cancers." (PMID 40361374, 2025). "Here, we developed the ColoCaller test, which simultaneously detects the methylation status of the SDC2, TFPI2, WIF1, and NDRG4 genes in stool DNA, to optimize the screening of gastric and colorectal cancer in high-risk populations." (PMID 35419280, 2022). "As a non-invasive detection method, the dual detection of SDC2/TFPI2 will be an easy and precise screening tool for colorectal cancer and its precancerous lesions." (PMID 35004840, 2021). "Loss of TFPI2 function has been associated with pro-invasiveness and methylation of TFPI2 is considered an independent prognostic factor for CRC as it has been associated with later stages of carcinogenesis and advanced colorectal cancer." (PMID 33030559, 2021). "To investigate the in vivo relevance of such findings, we analysed LCT13b and TFPI-2 expression levels by real-time RT–PCR in matched normal and tumour colorectal tissue samples from 27 sporadic cases of colorectal cancer." (PMID 23703216, 2013). "Methylated SDC2 and TFPI2 are widely used for colorectal cancer (CRC) detection." (PMID 35227195, 2022). "TFPI2 may take part in promoting colorectal cancer by changing the DNA methylation status of colon epithelial cells." (PMID 36505458, 2022). "Also, research showed that tissue factor pathway inhibitor 2 (TFPI2) methylation was noticeable in colorectal cancers of human." (PMID 34986742, 2022). "Detection rate of TFPI2 in colorectal cancer tissues with the SDC2 β value lower than 0.2." (PMID 35004840, 2021). "Subsequently, we screened four genes (ALOX15, GHRHR, TFPI2 and TKTL1) with aberrant methylation and aberrant hydroxymethylation at some genome position by functional enrichment analysis as candidate genes associated with colorectal cancer." (PMID 27546520, 2016). "Therefore, vascular thrombosis, hypoxia and necrosis induced by TFPI2 low-expression could be the main reasons for aggressive phenotypes in gastric and colorectal cancer pathways." (PMID 29137404, 2017). "Methylated TFPI2 has been considered a potential tumour marker for the early prediction of tumorigenesis, including HCC, colorectal cancer and oesophagal cancer." (PMID 35501390, 2022). "Bioinformatics analyses reveal prevalent hypermethylation of TFPI2 was an early event in tumorigenesis of colorectal caner, and expression of TET1 and TFPI2 was positive correlation in colorectal cancer and normal tissue." (PMID 30651599, 2019). "Over the last decade, TFPI2 has been identified as a TSG in several types of cancer, including colorectal cancer (CRC)." (PMID 31405379, 2019).
glioblastoma (16 papers, 2005 to 2026). The most malignant astrocytic tumor (WHO grade IV). "Epigenetic inactivation via hypermethylation of promoter CpG island of TFPI2 is associated with TFPI2silencing in pancreatic ductal adenocarcinoma, gastric cancer, non-small-cell lung cancer and glioblastomas, and contributes to the aggressive phenotype of various tumors." (PMID 32248791, 2020). "miR-195 also inhibits TFPI2 in glioblastoma, gallbladder cancer, and preeclampsia, where it enhances trophoblast growth via human umbilical cord-derived mesenchymal stem cells vesicles." (PMID 40361374, 2025). "M2 TAMs are also common in TFPI2-overexpressing hepatocellular carcinoma and glioblastoma, where they drive tumor progression via angiogenesis and immune suppression." (PMID 40361374, 2025). "In contrast, TFPI2 was found to be upregulated in glioblastoma 14, melanoma 15, ovarian clear cell carcinoma 16, and colorectal cancer." (PMID 40765823, 2025). "In fact, adenoviral-mediated TFPI-2 gene transfer inhibited the growth of a human glioblastoma (GBM) cell line and laryngeal squamous cell carcinoma in a nude mouse model." (PMID 39153052, 2024). "A previous study reported that TFPI2 is a target of miR-195, involved in the regulation of glioblastoma cell proliferation and apoptosis." (PMID 37559681, 2023). "Even though this study focused on AC003092.1 as a potential therapeutic target for glioblastoma patients, the conducted investigation indicated that this lncRNA regulates TFPI2 expression through the miR-195/TFPI2 axis in glioblastoma." (PMID 37569483, 2023). "Studies on TFPI2 have mainly focused on glioblastoma, which is related to neurodevelopment." (PMID 39299017, 2024). "Moreover, miR-195 and TFPI-2 was identified to interact with TMZ resistance in glioblastoma, which explains the poor prognosis of GB patients under TMZ treatment." (PMID 30442884, 2018). "However, emerging evidence indicates that TFPI2 promotes tumor progression in glioblastoma, melanoma, and other cancers by fostering an immunosuppressive tumor microenvironment, mediating pathological ECM remodeling, and enhancing angiogenesis and hematogenous dissemination." (PMID 42216563, 2026). "Moreover, TFPI-2 protein is undetectable by Western blotting in high-grade glioblastomas." (PMID 15685245, 2005). "In glioblastoma, lncRNA AGAP2-AS1 recruits lysine-specific histone demethylase 1 (LSD1) and enhancer of zeste homolog 2 (EZH2) to the TFPI2 promoter, leading to H3K27me3 and DNMT1-mediated methylation, silencing TFPI2 and promoting tumor progression." (PMID 40361374, 2025). "In glioblastoma, AGAP2-AS1 acts as a guide and is suggested to inhibit TFPI2 expression through EZH2 and LSD1 binding." (PMID 37569483, 2023). "In glioblastoma patients, the AC003092.1 showed a positive correlation with the gene expression of its predicted target gene TFPI2 (tissue factor pathway inhibitor 2) (Spearman r = 0.6, p < 0.001)." (PMID 33815468, 2021). "Glioblastoma (GBM) is a highly aggressive brain tumor characterized by extensive crosstalk between glioblastoma stem cells (GSCs) and immunosuppressive microglia, with our previous work identifying CLOCK and TFPI2 as key regulators of this interaction." (PMID 41842961, 2026). "In glioblastoma, AGAP2-AS1 could epigenetically silence TFPI2 expression by binding to EZH2 and LSD1 to promote GBM." (PMID 33815468, 2021).
melanoma (16 papers, 2010 to 2026). A malignant, usually aggressive tumor composed of atypical, neoplastic melanocytes. "Methylated TFPI2 DNA in serum from melanoma patients was more strongly associated with metastatic disease than primary disease." (PMID 34249699, 2021). "TFPI2 was overexpressed 65-fold in case 2 and has been reported to be essential for vasculogenic mimicry in melanoma." (PMID 40717170, 2025). "In the melanoma in vivo model, high levels of TFPI-2 have been correlated with worse outcomes in uveal melanoma (UM), but with better outcomes in cutaneous melanoma (CM)." (PMID 39153052, 2024). "Kondraganti and colleagues found that the reintroduction of TFPI-2 inhibits tumor invasion and growth in vitro and in vivo in a malignant melanoma cell line." (PMID 36900315, 2023). "One of the candidate genes tested was tissue factor pathway inhibitor 2 (TFPI2), which was found to be methylated in the sera of patients with melanoma with the magnitude of methylation being more pronounced in the metastatic setting." (PMID 38201222, 2023). "Here, we show that high levels of TFPI2 were statistically correlated with poor outcomes in UM individuals but better outcomes in CM individuals, which may be due to the few overlapping etiologies, mutation profiles, genetic signatures, and clinical behaviors of these two types of melanoma." (PMID 34249699, 2021). "On the other hand, TFPI2 also induced invasion of hepatocellular carcinoma cells and contributed to vasculogenic mimicry plasticity of melanoma." (PMID 34249699, 2021). "We also examined the correlation between TFPI2 and baseline characteristics of melanoma patients from TCGA-UM." (PMID 34249699, 2021). "Transcriptional silencing of TFPI2 by promoter methylation has been reported in a variety of tumors including melanoma." (PMID 34249699, 2021). "Angiotropism and TFPI2 expression were examined in surgical specimens of melanoma by immunohistochemical staining." (PMID 34249699, 2021). "In MM, however, hypermethylation of TFPI2 was reportedly shown in metastasis‐derived melanoma cell lines, while the tumorigenic roles of TFPI2 in MM have not been fully investigated." (PMID 32406600, 2020). "JMJD3 was found to interact with SMAD1 and SMAD4, crucial transcription factors in BMP signaling and upregulated CCL2 and tissue factor pathway inhibitor 2 (TFPI2) in melanoma cells." (PMID 31701394, 2019). "TFPI2 is a serine protease inhibitor in the extracellular matrix that is known to be heavily methylated in an assortment of cancers, including melanoma." (PMID 20520718, 2010). "We next examined whether TFPI2 is correlated with melanoma angiotropism by examining TFPI2 expression and distribution and its correlation with the presence of angiotropism in the TMU-CM cohort." (PMID 34249699, 2021). "TFPI2 downregulation weakened the perivascular migration of highly invasive melanoma cells." (PMID 34249699, 2021). "We found that malignant melanoma can be stratified into at least two subgroups based on promoter methylation status, and that High‐methylation subgroup involving TFPI2 methylation exhibits advanced tumor phenotypes, characterized by thicker progression and worse prognosis." (PMID 32406600, 2020). "Furthermore, hypermethylation of TFPI2 in the serum of melanoma patients has been suggested as a biomarker for metastatic disease." (PMID 29212200, 2017). "Suppression of TFPI-2 gene expression is frequently found in melanoma, liver and pancreatic cancer." (PMID 21062455, 2010). "However, TFPI2 has also been shown to promote the migration of tumor cells, support firm adhesion of endothelial cells, and enhance the formation of vasculogenic-like networks by aggressive melanoma cells." (PMID 34249699, 2021).
melanoma (continued). "Furthermore, we found that TFPI2 could promote angiotropic migration of melanoma cells and that higher TFPI2 expression was correlated with worse and better survival of UM and CM patients, respectively, indicating its potentially diverse effects in a context-dependent manner." (PMID 34249699, 2021). "Indeed, DNA methylation of specific genes, such as Tissue Factor Pathway Inhibitor 2 (TFPI2), has been shown to be correlated with advanced melanoma." (PMID 36835424, 2023). "Since hypermethylation at the promoter region of tumor suppressor genes, e.g., RARB2, TFPI2, RASSF1A, MGMT, and PTEN, helped to distinguish melanoma patients from healthy individuals, epigenetic changes in cfDNA may also serve as diagnostic markers in melanoma." (PMID 34575876, 2021).
pancreatic cancer (16 papers, 2005 to 2025). "Fat mass and obesity-associated protein (FTO) reduces TFPI2 via N6-methyladenosine (m6A) RNA demethylation, promoting pancreatic cancer and enhancing keratinocyte proliferation and angiogenesis during wound healing." (PMID 40361374, 2025). "Curcumin inhibits pancreatic cancer cell invasion by upregulating TFPI2 and suppressing ERK- and JNK-driven EMT." (PMID 40361374, 2025). "In pancreatic cancer, miR-23a and miR-20a-5p target TFPI2, enhancing proliferation, migration, and invasion." (PMID 40361374, 2025). "A previous study reported that miR-23a downregulates TFPI2 expression in pancreatic cancer cells and exacerbates their malignant characteristics, thus acting as an oncogene." (PMID 39199316, 2024). "TFPI2 (Tissue factor pathway inhibitor-2), Kunitz-type serine proteinase, and a presumed tumor suppressor gene was associated with PNI in pancreatic carcinoma tissue." (PMID 35571032, 2022). "TFPI-2 mRNA was undetectable in many pancreatic cancer cell lines and in primary pancreatic ductal neoplasms." (PMID 15969748, 2005). "Silencing LHX6 in pancreatic cancer enhances proliferation, likely through TFPI2 regulation." (PMID 40361374, 2025). "TFPI2 hypermethylation has been detected in tissue from intraductal papillary mucinous neoplasms, in pancreatic cancer tissue and in pancreatic juice from pancreatic cancer patients." (PMID 29212200, 2017). "However, expression of the TFPI-2 gene in pancreatic cancer cells has resulted in markedly suppressed proliferation, migration, and invasive potential in vitro." (PMID 15969748, 2005). "miR-377 enhances TFPI2 by downregulating DNA methyltransferase 1 (DNMT1), promoting apoptosis in pancreatic cancer." (PMID 40361374, 2025). "Transfection of miR-148b or miR-152 in pancreatic cancer cells reactivated tumor suppressor genes such as BNIP3, SPARC, PENK, and TFPI-2 by downregulating DNMT1." (PMID 36959680, 2023). "First, we have analyzed in cfDNA from eight mPDAC patients the methylation levels of five genes BMP3, NPTX2, SPARC, TFPI2 and SFRP1 known to be aberrantly methylated in pancreatic cancer." (PMID 37481552, 2023). "In pancreatic cancer cells, although FTO still inhibited the m6A modification of its target tissue factor pathway inhibitor-2 (TFPI2), unlike PD-L1, the mRNA expression of TFPI2 was decreased because less TFPI2 was bound by YTHDF139." (PMID 38438714, 2024). "The prognostic value of TFPI2 hypermethylation has not previously been evaluated in pancreatic cancer." (PMID 29212200, 2017). "After conducting a thorough analysis of published studies on cfDNA methylation in pancreatic cancer, as well as a comparative methylation analysis using the TCGA database, we have identified a set of consistently reported hypermethylated genes: BMP3, NPTX2, SFRP1, SPARC, and TFPI2." (PMID 37481552, 2023). "Cell-free DNA hypermethylation of BMP3, MESTv2, SST, TFPI2, TAC1, ALX4, HIC1, SFRP2, SEPT9v2 and WNT5A has not previously been described in the literature in relation to pancreatic cancer." (PMID 27891190, 2016).
hepatocellular carcinoma (14 papers, 2012 to 2025). A malignant tumor that arises from hepatocytes. "Then, we evaluated the expression level of SERPINE1, VCAN, and TFPI2 in human hepatocellular carcinoma cells." (PMID 36407083, 2022). "We then evaluated the expression of SERPINE1, VCAN, and TFPI2 in the hepatocellular carcinoma cohort of the TCGA cohort." (PMID 36407083, 2022). "We finally discovered that SERPINE1, VCAN, and TFPI2 play an important role in hepatocellular carcinoma." (PMID 36407083, 2022). "In contrast to the tumor suppressor-like features of TFPI2, there is a report that demonstrates a paradoxical pro-invasive function of TFPI2 in hepatocellular carcinoma cells in vitro." (PMID 34009487, 2021). "TFPI2 is frequently silenced in human hepatocellular carcinoma via epigenetic alterations, including promoter methylation and histone deacetylation." (PMID 35004840, 2021). "In the present study, we sought to identify the factors involved in the RARα-mediated transcriptional regulation of the tumor suppressor gene and the tissue factor pathway inhibitor 2 (TFPI2) in hepatocellular carcinoma (HCC)." (PMID 29757260, 2018). "Our findings contrast with previous studies in vitro, which demonstrated that ectopic expression of TFPI-2 significantly inhibited cell proliferation in hepatocellular carcinoma, nasopharyngeal carcinoma cell lines and Human retinal endothelial cells." (PMID 22208663, 2012). "Finally, in order to explore the function of 3 key genes (SERPINE1, VCAN, and TFPI2) in hepatocellular carcinoma patients, we then performed the GSVA enrichment analysis." (PMID 36407083, 2022). "Additionally, we also evaluated the potential function of SERPINE1, VCAN, and TFPI2 in a hepatocellular carcinoma cohort." (PMID 36407083, 2022). "However, consistent with our finding, TFPI2 hypermethylation in tissue from hepatocellular carcinoma has been found to correlate with advanced cancer stage and a significantly shorter survival time." (PMID 29212200, 2017). "In addition, three glucose metabolism-related genes (SERPINE1, VCAN, and TFPI2) may be potential targets for the immunotherapy of patients with NAFLD-hepatocellular carcinoma." (PMID 36407083, 2022). "In addition, three glucose metabolism-related genes (SERPINE1, VCAN, and TFPI2) may be the potential targets for the immunotherapy of patients with NAFLD-hepatocellular carcinoma." (PMID 36407083, 2022). "In addition, TFPI2 is specifically expressed in the monocytes of hepatocellular carcinoma." (PMID 36407083, 2022). "Furthermore, promoter methylation of TFPI2 is a poor prognostic factor of hepatocellular carcinoma." (PMID 34009487, 2021). "This antitumor effect is supported by the fact that TFPI2 is silenced in various tumors including hepatocellular carcinoma (HCC)." (PMID 29757260, 2018). "For example, compared to matched normal liver, human hepatocellular carcinomas (HCC) significantly underexpress TFPI-2 in approximately 90% of cases; however, more than 50% of HCCs retain a non-methylated promoter." (PMID 23703216, 2013).
lung cancer (12 papers, 2005 to 2025). A malignant neoplasm involving the lung. "On the other hand, the underlying mechanisms for the de novo methylation of the TFPI-2 gene in lung cancer cells also remain to be determined." (PMID 15685245, 2005). "According to another study, TFPI2 gene methylation is an independent predictor of poor prognosis in nonsmall cell lung cancer patients." (PMID 36407083, 2022). "Downregulation of TFPI-2 could thus enhance the invasive potential of neoplastic cells in several cancers, including lung cancer." (PMID 15685245, 2005). "In addition, decreased TFPI-2 gene expression and promoter hypermethylation were more frequently associated with advanced stages (i.e. III and IV) of lung cancer." (PMID 15685245, 2005). "TMPRSS4 expression in NSCLC samples correlates negatively with that of tissue factor pathway inhibitor 2 (TFPI-2), and TFPI-2 partially inhibits transcription of TMPRSS4, leading to reduced lung cancer cell growth." (PMID 37009799, 2023). "Such previous studies identified the RASSF1A, PITX2, SHOX2, TFPI-2, FHIT, p16, CDH13, and APC genes as predictors of recurrence of lung cancers." (PMID 23544068, 2013). "Research in cell lines has revealed that TFPI-2 is correlated with lower invasiveness of GBM SNB19 human lung cancer A549, prostate cancer LNCaP, fibrosarcoma HT-1080, pancreatic ductal adenocarcinoma, gastric cancer (GC), BC), amelanotic melanoma C-32 and thyroid cancer cells." (PMID 39153052, 2024). "Additionally, they showed that incubation of pulmonary fibroblasts with conditioned media from cancer cells with silenced TFPI-2 increased MMP expression and promoted lung cancer cell invasion and metastases." (PMID 39153052, 2024).